C9orf72 (C9orf72-SMCR8 complex subunit)
Diseases named in the same sentence as C9orf72 in open-access papers (continued):
Sharing a sentence is not in itself a finding about the gene and the disease.
amyotrophic lateral sclerosis (continued). "G4-PROTAC is designed for specific degradation of a G4-binding protein (RHAU/DHX36) which has been reported to be highly expressed in tissues of C9orf72-linked amyotrophic lateral sclerosis (ALS) patients and thus represents an important therapeutic target." (PMID 35625576, 2022). "The most common known monogenetic cause of amyotrophic lateral sclerosis (ALS) is an intronic hexanucleotide repeat expansion (HRE) in C9orf72." (PMID 36070099, 2022). "Hypermethylation also occurs in the G4C2 repeat expansion in C9orf72, which is the most common known cause of amyotrophic lateral sclerosis (ALS) and frontotemporal lobar degeneration (FTLD)." (PMID 35252421, 2022). "As much as 85% of FTD cases caused by C9orf72 expansions are associated with the bvFTD subtype, while 22.31% of C9orf72 expansion carriers display additional degeneration of motor neurons or FTLD with amyotrophic lateral sclerosis (FTLD-ALS)." (PMID 33802612, 2021). "The (CCCCGG)n repeat expansion in C9orf72 segregates with up to 40% of familial amyotrophic lateral sclerosis (ALS) cases and is one of few established causes of the disease." (PMID 33830997, 2021). "The most common genetic cause of amyotrophic lateral sclerosis (ALS) is a GGGGCC (G4C2) hexanucleotide repeat expansions in first intron of the C9orf72 gene." (PMID 33129345, 2020). "An example of which is the expansion in C9orf72 associated with amyotrophic lateral sclerosis (ALS)." (PMID 32345345, 2020). "The hexanucleotide expansion GGGGCC located in C9orf72 gene represents the most common genetic cause of amyotrophic lateral sclerosis (ALS) and frontotemporal lobar dementia (FTLD)." (PMID 31991801, 2020). "We had one amyotrophic lateral sclerosis (ALS) case with a C9orf72 gene mutation and one multiple system atrophy (MSA)." (PMID 33143239, 2020). "The hexanucleotide (GGGGCC) repeat expansion in the C9orf72 gene is the underlying genetic cause in approximately half of the familial amyotrophic lateral sclerosis (ALS) cases and in about 10% of the sporadic ALS cases." (PMID 33089205, 2020). "The hexanucleotide (GGGGCC) repeat expansion in the chromosome 9 open reading frame 72 (C9orf72) gene is the underlying genetic cause in approximately half of the familial amyotrophic lateral sclerosis (ALS) cases and in about 10% of the sporadic ALS cases." (PMID 31791419, 2019). "A repeat expansion mutation in the C9orf72 gene is the most common cause of familial amyotrophic lateral sclerosis (ALS) in people of Northern European ancestry and accounts for 5-10% of sporadic ALS cases in Europe and the USA." (PMID 30568632, 2018). "A hexanucleotide repeat expansion (HRE) within the chromosome 9 open reading frame 72 (C9orf72) gene is the most prevalent cause of amyotrophic lateral sclerosis/fronto-temporal dementia (ALS/FTD)." (PMID 30454072, 2018). "Expanded GGGGCC repeats in the first intron of the C9orf72 gene represent the most common cause of familial amyotrophic lateral sclerosis (ALS), but the mechanisms underlying repeat-induced disease remain incompletely resolved." (PMID 28072389, 2017). "The GGGGCC (G4C2)repeat expansion in the non-coding region of the C9orf72 protein is the most common cause of sporadic and familial forms of amyotrophic lateral sclerosis (ALS) and frontal temporal dementia (FTD)." (PMID 28261044, 2017). "Hexanucleotide repeat expansions in C9orf72 are the most common cause of amyotrophic lateral sclerosis (ALS) and frontotemporal degeneration (FTD) (c9ALS/FTD)." (PMID 26869068, 2016). "Abnormal expansion of a GGGGCC hexanucleotide (G4C2) repeat in a noncoding region of C9ORF72 is the most commonly identified genetic variant associated with both familial amyotrophic lateral sclerosis (ALS) and familial frontotemporal dementia (FTD)." (PMID 27877110, 2016).
amyotrophic lateral sclerosis (continued). "Expanded GGGGCC repeats in intron 1 of the C9orf72 gene represent the most common cause of familial amyotrophic lateral sclerosis (ALS) and familial frontotemporal degeneration, though how this genetic change results in neuronal injury is not yet understood." (PMID 24866055, 2014). "FTLD shares clinical, genetic and pathological features with amyotrophic lateral sclerosis (ALS), and C9orf72 mutation is the most common known cause of ALS." (PMID 24170096, 2013). "The C9ORF72 gene mutation is a major cause of amyotrophic lateral sclerosis (ALS)." (PMID 41294820, 2025). "We have investigated changes in chromosome conformation, nuclear organization, and transcription during differentiation and maturation of control and mutant motor neurons harboring hexanucleotide expansions in the C9orf72 gene that cause amyotrophic lateral sclerosis (ALS)." (PMID 41040221, 2025). "For instance, mutations in GRN invariably lead to FTLD-TDP type A while C9orf72 repeat expansions are mainly linked to FTLD-TDP type B, which is often accompanied by amyotrophic lateral sclerosis (ALS)." (PMID 40619440, 2025). "C9orf72 REs have been well characterized in the Amyotrophic lateral sclerosis / frontotemporal spectrum disorders." (PMID 39425080, 2024). "Amyotrophic lateral sclerosis (ALS) and FTD patients carrying a C9orf72 repeat expansion mutation typically show neuronal accumulations of the expanded RNA repeats into cytoplasmic RNA foci." (PMID 38585368, 2024). "To test if this observation also holds for other amyotrophic lateral sclerosis mutations, we examined KCNV1 expression in MNs differentiated from iPSCs harbouring C9orf72 hexanucleotide repeat expansions." (PMID 38911266, 2024). "C9orf72 carriers usually develop bvFTD, amyotrophic lateral sclerosis or both, and the thalamus is one of the earliest affected areas." (PMID 38699560, 2024). "There is increasing evidence for disruption of nucleocytoplasmic transport of proteins and RNA in neurodegenerative disease, including for example, C9orf72-mediated amyotrophic lateral sclerosis and FTD." (PMID 39009859, 2024). "C9orf72 mutations are the most common form of familial amyotrophic lateral sclerosis (C9-ALS)." (PMID 37887320, 2023). "Repeat expansions in genes other than C9orf72 and ATXN2 have been recently associated with Amyotrophic Lateral Sclerosis (ALS)." (PMID 36823368, 2023). "In the amyotrophic lateral sclerosis (ALS) mouse model, the aggregates-related protein C9orf72 can cause ER stress response." (PMID 37239937, 2023). "We explore the therapeutic potential of PSNAs by delivering siRNA duplexes against C9orf72, a target for genetic treatment of the neurodegenerative disease amyotrophic lateral sclerosis (ALS), to motor-neuron-like cells." (PMID 37260495, 2023). "These polymeric SNAs are used to deliver siRNA duplexes against C9orf72, a genetic target with therapeutic potential for amyotrophic lateral sclerosis, to motor neuron-like cells." (PMID 37260495, 2023). "To date, more than 40 genes have been identified to be associated with amyotrophic lateral sclerosis, and SOD1, TARDBP, FUS, and C9ORF72 are the most common pathogenic genes in familial ALS (FALS)." (PMID 36672065, 2023). "Amyotrophic lateral sclerosis (ALS) individuals carrying the hexanucleotide repeat expansion (HRE) in the C9orf72 gene (C9Pos) have been described as presenting distinct features compared to the general ALS population (C9Neg)." (PMID 36308529, 2023). "C9orf72 mutations have been found in almost 12% of patients with FTD and are also associated with some forms of amyotrophic lateral sclerosis (ALS)." (PMID 37761400, 2023). "For example, expansions in C9orf72 can present as either amyotrophic lateral sclerosis or frontotemporal dementia." (PMID 35182509, 2022).
amyotrophic lateral sclerosis (continued). "AAV technology has been used to generate mouse models of other neurodegenerative diseases, including C9orf72-associated amyotrophic lateral sclerosis (ALS), Alzheimer’s disease, Huntington’s disease and SCA36, and these models successfully recapitulate disease features." (PMID 35386195, 2022). "In the amyotrophic lateral sclerosis case studies, examining penetrance for variants in the SOD1 and C9orf72 genes, we make novel penetrance estimates which correspond closely to understanding of the disease." (PMID 36522764, 2022). "He described his lab’s work in investigating how a hexanucleotide (GGGGCC) repeat expansion in C9orf72 promotes Amyotrophic lateral sclerosis (ALS)." (PMID 35485383, 2022). "Mutations in autophagy regulator protein C9ORF72 and in DNA/RNA binding proteins TDP-43 and FUS are associated with Amyotrophic Lateral Sclerosis (ALS) disease." (PMID 36009362, 2022). "The hexanucleotide expansion located in the first intron of the C9orf72 gene affects 40% of familial amyotrophic lateral sclerosis (ALS) patients and causes a devastating disease that involves the progressive degeneration of motor neurons and muscle denervation." (PMID 36290620, 2022). "For example, in seven patients with amyotrophic lateral sclerosis or other motor neuron disease, expansions were identified in AR (n=4) and C9orf72 (n=3)." (PMID 35182509, 2022). "Repeat expansions, including those in C9orf72 and ATXN2, have been implicated in amyotrophic lateral sclerosis (ALS)." (PMID 35599735, 2022). "A gene mutated in amyotrophic lateral sclerosis (ALS) and frontal temporal degeneration (FTD), called C9orf72, was recently identified as a GAP for ARF1." (PMID 34368129, 2021). "More recently, from 16 antibodies (from seven vendors) against C9ORF72—a human protein specific to amyotrophic lateral sclerosis (ALS)—only one worked well in immunofluorescence, while two worked for Western blotting." (PMID 35056102, 2021). "For example, in the zebrafish model of amyotrophic lateral sclerosis (ALS), overexpression of mutant SOD1 leads to aberrant branching and shortening of the primary motor axons, whereas knockdown of C9orf72, associated with ALS, causes aberrant branching of CaP motor axons." (PMID 33973627, 2021). "TDP-43 is a major neuropathological protein accumulating in familial FTD (linked to mutations in GRN and C9orf72 genes) as well as in amyotrophic lateral sclerosis (ALS), and it normally contains various physiological functions such as RNA translation, autophagy, and synaptic plasticity." (PMID 33925655, 2021). "Amyotrophic lateral sclerosis (ALS) is the most common neurodegenerative disease of the motor neuron system, which is generally caused by mutations in the chromosome 9 open reading frame (C9orf72) gene." (PMID 34389067, 2021). "Mutations in C9orf72 are the most common genetic cause of amyotrophic lateral sclerosis (ALS)." (PMID 31841614, 2020). "C9orf72 is now believed to be the largest single genetic contributor to amyotrophic lateral sclerosis (ALS), accounting for perhaps 40% of familial ALS and 10% of sporadic ALS." (PMID 31058853, 2019). "C9ORF72 mutations are the most common cause of familial frontotemporal lobar degeneration (FTLD) and amyotrophic lateral sclerosis (ALS)." (PMID 30705258, 2019). "Besides FTLD, the C9orf72 repeat expansion also causes up to 40% of familial amyotrophic lateral sclerosis (ALS) cases in these populations." (PMID 31561355, 2019). "We investigated whether the C9orf72 repeat expansion is associated with specific clinical features, comorbidities, and prognosis in patients with amyotrophic lateral sclerosis (ALS)." (PMID 31156370, 2019). "Using fibroblasts and reprogrammed induced astrocytes from C9orf72 and sporadic amyotrophic lateral sclerosis cases we measured the production rate of reduced nicotinamide adenine dinucleotides (NADH) from 91 potential energy substrates simultaneously." (PMID 31647549, 2019).
amyotrophic lateral sclerosis (continued). "Many Amyotrophic Lateral Sclerosis (ALS)-linked mutations cause accumulation of stress granules, and most ALS cases are caused by repeat expansions in C9ORF72." (PMID 30022074, 2018). "Mutations in C9ORF72 are the most common cause of familial amyotrophic lateral sclerosis (ALS)." (PMID 29367641, 2018). "An intronic GGGGCC expansion in C9orf72 is the most common known cause of both frontotemporal lobar dementia (FTLD) and amyotrophic lateral sclerosis (ALS)." (PMID 28420437, 2017). "A hexanucleotide repeat expansion mutation in chromosome 9 open reading frame 72 (C9orf72) is the most common known genetic cause of amyotrophic lateral sclerosis (ALS), a fatal neurodegenerative disease characterized by the progressive loss of corticospinal, brainstem and spinal motor neurons." (PMID 28720882, 2017). "Furthermore, C9orf72 (chromosome 9 ORF 72) a protein mutated in the neurodegenerative disorder ALS (amyotrophic lateral sclerosis), has recently been reported to regulate the ULK1 complex." (PMID 29233870, 2017). "A hexanucleotide repeat expansion (HRE) of a noncoding GGGGCC repeat within the Chromosome 9 open reading frame 72 (C9orf72) gene has been identified as a major cause of amyotrophic lateral sclerosis (ALS, MIM: 612069) and frontotemporal lobar degeneration (FTLD, MIM: 600274)." (PMID 27288208, 2016). "TDP-43 inclusions have also been identified in the majority of amyotrophic lateral sclerosis (ALS) and FTD-MND cases, in particular in patients with mutations of the C9orf72 gene." (PMID 26388768, 2015). "GGGGCC repeat expansions within intron 1 of the C9ORF72 gene are the most common cause of familial amyotrophic lateral sclerosis (ALS) and familial frontotemporal degeneration (FTD), though how this genetic change results in neuronal injury is not yet understood." (PMID 26016851, 2015). "Similarly, motor neurone type symptomology is also variably associated with several fFTD‐implicated genes, particularly C9orf72, and can lead to an overlapping syndrome of FTD‐related amyotrophic lateral sclerosis (FTD‐ALS)." (PMID 39801084, 2025). "None of the MFN2-amyotrophic lateral sclerosis patients tested positive for the pathogenic C9orf72 gene expansion, nor did they exhibit mutations in the SOD1 gene or the known mutational hotspots of the TARDBP (exon 6) and FUS (exons 13-14-15) genes." (PMID 39315308, 2024). "We likewise identified significant differences comparing patients with C9orf72 mutations with sporadic amyotrophic lateral sclerosis patients (n = 2178), i.e. patients without a positive family history and without any known causative genetic mutation." (PMID 37006326, 2023). "Therefore, it can be concluded that neuropsychological deficits are more accentuated in C9orf72, although, compared to sporadic amyotrophic lateral sclerosis, this finding was only significant for verbal fluency." (PMID 37006326, 2023). "Intron 2 retention in RFC1 pre-mRNA across various tissues has been identified in patients, which is known as a common event associated with other disease-causing guanine-cytosine-rich intronic expansions, like myotonic dystrophy type 2 and C9orf72-amyotrophic lateral sclerosis." (PMID 36061987, 2022). "Therefore, pridopidine may ameliorate the TFEB transport deficit in the C9orf72 subtype of amyotrophic lateral sclerosis-frontotemporal lobar degeneration (ALS-FTD), where the mutation damages the nucleocytoplasmic transport of TFEB." (PMID 36518658, 2022). "Further, SOD1, C9orf72, and SMN1 have been identified as causative genes for amyotrophic lateral sclerosis and spinal muscular atrophy, in which the viability of spinal motor neurons is decreased, and treatment strategies targeting these genes are under development." (PMID 35743104, 2022).
amyotrophic lateral sclerosis (continued). "Common neuromuscular repeat expansion disorders not detectable via NGS include myotonic dystrophy 1 and 2, facioscapulohumeral muscular dystrophy 1 (FSHD1), oculopharyngeal muscular dystrophy (OPMD), oculopharyngodistal myopathies, and C9orf72-related amyotrophic lateral sclerosis." (PMID 36313509, 2022). "However, a recent study has compared the CSF proteome of C9orf72-related FTD and C9orf72-related amyotrophic lateral sclerosis (ALS)." (PMID 36274975, 2022). "This approach is validated using genome sequence data for 259 cases of amyotrophic lateral sclerosis, of which 24 are positive for a large repeat expansion in C9orf72, showing that REscan statistics readily discriminate repeat expansion carriers from non-carriers." (PMID 32845284, 2021). "The onset of amyotrophic lateral sclerosis (ALS) may be related to neonatal dysfunction due to imbalances in excitation and inhibition, perhaps arising from the mutation of genes involved in neurodevelopment (i.e., C9orf72)." (PMID 34924930, 2021). "A hexanucleotide repeat (GGGGCC, G4C2) expansion in chromosome 9 open reading frame 72 (C9orf72) [GenBank: JN681271] was discovered to likely be the most frequent genetic cause of bvFTD, FTD with motor neuron disease (FTD-MND), and amyotrophic lateral sclerosis (ALS) in some populations." (PMID 34248820, 2021). "Another gene lacking functional annotation is C9orf72, the major locus implicated in human amyotrophic lateral sclerosis." (PMID 32793601, 2020). "GGGGCC hexanucleotide repeat expansion (HRE) in the non-coding region of chromosome 9 open reading frame 72 (C9orf72) (C9-HRE) is the major genetic cause of familial FTLD (12–48%) and amyotrophic lateral sclerosis (ALS) (24–46%) cases and 6–20% of sporadic cases for both diseases." (PMID 31156371, 2019). "The pathological expansion of a hexanucleotide repeat in the C9orf72 gene is the most common genetic mutation identified in patients with amyotrophic lateral sclerosis (ALS), reported in 40–50% of patients with familial ALS and 5–10% of patients with sporadic ALS." (PMID 31156370, 2019). "Genomic instability, included failures in DNA repair, is likewise thought to contribute to pathogenesis as a consequence of C9orf72 repeat expansions (a noncoding region of chromosome 9) in amyotrophic lateral sclerosis and a number of other degenerative diseases including Alzheimer’s disease." (PMID 29618789, 2018). "Of these unique cisSNP, those that associate with cerebellar levels of C9orf72 in non–ADs are interesting, as these variants were previously identified in GWAS of amyotrophic lateral sclerosis (ALS), where C9orf72 was one of the candidate genes at the disease locus." (PMID 22685416, 2012). "Concurrently, PML-NB dysfunctions have been associated with pathological conditions including, but not limited to, APL and C9orf72 amyotrophic lateral sclerosis (ALS)." (PMID 41008598, 2025). "Approximately 40–55% of amyotrophic lateral sclerosis (ALS) cases are attributed to mutations in over 50 identified ALS-associated genes; among these, pathogenic mutations in SOD1, C9ORF72, FUS, and TARDBP are the most prevalent." (PMID 38927671, 2024). "Amyotrophic lateral sclerosis (ALS) is a degenerative condition affecting the motor neurones, characterized by a multifaceted genetic makeup—mutations in genes such as SOD1, C9orf72, TARDBP, and FUS cause ALS." (PMID 39759457, 2024). "The proteins implicated in amyotrophic lateral sclerosis (ALS), including TAR DNA-binding protein 43 (TDP-43), fused in sarcoma (FUS), superoxide dismutase 1 (SOD1), and chromosome 9 open reading frame 72 (C9orf72) repeat peptides, are also related to the DDR." (PMID 39063148, 2024). "Though C9orf72, GRN and MAPT mutations most often result in bvFTD, they occasionally result in other neurodegenerative syndromes including primary progressive aphasia, amyotrophic lateral sclerosis, corticobasal syndrome, progressive supranuclear palsy, and parkinsonism." (PMID 39568670, 2024).